ABCA4 (ATP binding cassette subfamily A member 4)
Diseases named in the same sentence as ABCA4 in open-access papers (continued):
Sharing a sentence is not in itself a finding about the gene and the disease.
Stargardt disease (continued). "Functional impairment of the ABCA4 protein is responsible for a wide range of retinal degeneration phenotypes, including Stargardt disease 1 (STGD1), cone–rod dystrophy 3 (CRD3), retinitis pigmentosa 19 (RP19), and other conditions collectively referred to as ABCA4-associated retinopathies." (PMID 40606666, 2025). "Given the relatively mild phenotype in ABCA4 mutant mice, developing ABCA4 rhesus macaque models could significantly advance research and development of therapeutics for Stargardt disease and related ABCA4 conditions." (PMID 38969634, 2024). "ABCA4 (ATP Binding Cassette Subfamily A Member 4) encodes an ATP-binding cassette (ABC) superfamily transmembrane protein in the retina photoreceptor cells, and mutations in this gene cause Stargardt Disease 1, Retinitis Pigmentosa 19, Cone-Rod Dystrophy 3 and Age-related macular degeneration." (PMID 38548946, 2024). "Additionally, the delivery of the wild-type human ABCA4 gene into Abca4−/− mice via lentiviral vectors was shown to correct the Stargardt Disease phenotype by reducing the accumulation of the lipofuscin pigment A2E." (PMID 38391665, 2024). "In certain forms of Stargardt disease, there are no errors in the portions of the ABCA4 gene that encode for the structural blocks of the ABCA4 protein." (PMID 39201545, 2024). "The clinical/whole exome sequencing data from a Spanish cohort (the Fundación Jiménez Díaz cohort) of 52 probands with Stargardt disease and 26 probands with CRD, and one likely pathogenic or pathogenic variant in ABCA4 were investigated for the presence of c.6480-35A>G." (PMID 37779911, 2023). "The gene that emerged as involved in the incidence of Stargardt disease is ABCA4." (PMID 36836473, 2023). "Finally, REVeRT enabled the reconstitution of full-length ABCA4 after intravitreal injection in a mouse model of Stargardt disease." (PMID 37852949, 2023). "Prominent symptoms of glare and hemeralopia, significantly diminished full-field cone responses, and the AD inheritance pattern in Case 2b point towards AD cone dystrophy, rather than ABCA4-associated Stargardt disease." (PMID 38066771, 2023). "Biallelic variants in the ATP-binding cassette subfamily A member 4 (ABCA4, MIM 601691) gene give rise to ABCA4-associated retinopathies of which Stargardt disease (STGD1, MIM 248200) is the most common, with an estimated incidence between 1 in 8,000 and 1 in 10,000." (PMID 36552712, 2022). "AMD and Stargardt disease are induced by aging or an innate defect in ATP binding cassette subfamily A member 4 (ABCA4), and lipofuscin accumulates in RPE cells, which may cause blindness." (PMID 35504961, 2022). "The primary biochemical defect in Stargardt disease (STGD1) is the accelerated synthesis of cytotoxic lipofuscin bisretinoids, such as A2E, in the retinal pigment epithelium (RPE) due to mutations in the ABCA4 gene." (PMID 36227868, 2022). "The other two variants with elevated risk allele frequency, one was reported in CAGS but not HMC database, NM_000350.2(ABCA4):c.[5512C > G;5882G > A] linked to Stargardt disease, risk allele frequency 0.0207." (PMID 35046417, 2022). "ABCA4 gene mutations being more common than those of RPE65, it is not surprising that the contribution of DI variants emerged more readily in the pathogenesis of Stargardt disease." (PMID 34281261, 2021). "Multiple laboratories have effectively used this split vector approach in preclinical models: first for the delivery of the erythropoietin genomic locus, but later for retinal disease genes caused by variants in the MYO7A gene (Usher syndrome, type 1B) and the ABCA4 gene (Stargardt disease)." (PMID 34768969, 2021). "The ABCA transporter family is involved in the transport of a variety of lipid substrates, some of them being associated with severe recessive human inherited disorders such as Tangier disease (ABCA1), Stargardt disease (ABCA4) or harlequin ichthyosis (ABCA12)." (PMID 34638622, 2021).
Stargardt disease (continued). "Lentiviruses (LVs) are retroviruses with a larger packing capacity (8 kb), which makes them a compelling alternative to AAV vectors for those IRDs whose causative gene coding sequence exceeds the 4.7 kb limit, such as ABCA4-related Stargardt's disease and MYO7A-related Usher's syndrome type 1B." (PMID 34722588, 2021). "Similarly, gavaging ABCA4−/− mice (Stargardt disease) with 206 mg/day of omega-3 FA (172 mg EPA + 34 mg DHA) for three months resulted in no change in retinal DHA, although a 67% increase in retinal EPA (from 0.93% to 1.56% of total) was observed." (PMID 33053841, 2020). "It needs to be further elucidated whether the expression level of the ABCA4 gene in patients with Stargardt disease correlates with disease severity." (PMID 32413971, 2020). "The albino Abca4−/− mice, an animal model of Stargardt’s disease, used herein had a atRAL level similar to that of wild-type mice in adulthood (6–7 months) but had significantly lower 11cRAL levels and accumulated A2E faster, according to a recent report 30–32." (PMID 32641711, 2020). "ABCA4 is one of the most common disease-causing genes in inherited retinal degeneration (IRD), with a prevalence of approximately 1 in 10,000 people, and is considered the main cause of Stargardt disease 1 (STGD1; OMIM 248200)." (PMID 33261146, 2020). "Stargardt disease is an inherited form of macular degeneration characterized by juvenile-onset progressive vision loss, and is most commonly associated with defects in the ATP-binding cassette gene sub family A-4 transporter protein (ABCA4, or ABCR)." (PMID 33137979, 2020). "Here, the female proband presented with an isolated maculopathy initially diagnosed as atypical Stargardt disease at age 5 and underwent genetic testing of the entire ABCA4 gene, followed by whole exome sequencing (WES)‐based inherited retinal disease gene panel testing." (PMID 31721179, 2020). "Specifically, Sanger sequencing of ABCA4, PRPH2/RDS-peripherin, and ELOVL4 was negative except for Proband 1, who had a heterozygous ABCA4 missense variant (c.2588G>C; p.Gly863Ala) and no family history of Stargardt disease or cone-rod dystrophy." (PMID 30116628, 2018). "For example, the observed downregulation in ABCA4, a gene encoding a member of the of the ABC family of transporters that is expressed in retinal photoreceptors and its defect causes retinal degeneration such as Stargardt’s disease." (PMID 28472177, 2017). "The Abca4-KO mouse model has been utilized to understand the etiology of Stargardt disease." (PMID 25650393, 2015). "Compound heterozygous variants p.Y808X and p.G607R of the ATP-binding cassette, sub-family A (ABC1), member 4 (ABCA4) gene, which encodes the ABCA4 protein, a member of the ATP-binding cassette (ABC) transport superfamily, were identified as causative mutations for Stargardt disease of this family." (PMID 24632595, 2014). "In addition, Abca4 knockout mice, like individuals with Stargardt disease, show a delay in dark adaptation consistent with the delayed removal of all-trans retinal from outer segments following photobleaching." (PMID 24632595, 2014). "The root cause of Stargardt’s disease remains mutations in ABCA4 gene, but the complete manifestation of disease pathology is likely to be affected by alteration in molecular pathways resulting from the lack of a functional ABCA4." (PMID 40725253, 2025). "Interestingly, Stargardt disease, particularly with restricted macular atrophy, is infrequently associated with ERM, consistent with the current cohort where only 2.9% (n = 2/69, mean age 45.5 ± 29.0 years) of those with an ABCA4 genotype had ERM." (PMID 41465105, 2025). "As an example, we have calculated the likelihood of having autosomal recessive Stargardt disease after the laboratory finds only the frequent disease-associated ABCA4 Asn1868Ile variant and no second variant—in two different scenarios: one with and one without a clinical fit." (PMID 38778080, 2024).
Stargardt disease (continued). "Subretinal injection of the EIAV-ABCA4 vector (which contained the ABCA4 gene) in adults with Stargardt’s disease due to mutations in this gene demonstrated a lack of improvements in visual function, exacerbations of retinal pigment epithelium atrophy, and even chronic ocular hypertension." (PMID 38247870, 2024). "The reason is that the likelihood for true Stargardt disease is reduced from a priori 95% to a posteriori 67% if no ABCA4 variants are reported—even though the common Asn1868Ile variant was found, i.e., a likelihood reduction that is at least twice as large as after variant reporting (95% to 83%)." (PMID 38778080, 2024). "RBP4-inhibitors could be helpful if proven beneficial in ABCA4 Stargardt disease (NCT05244304)." (PMID 37331655, 2023). "Also, among the rare ABCA7 missense mutations, we observed mutations that affect amino acid residues that are conserved in ABCA1 and ABCA4, of which some correspond to established ABCA1 or ABCA4 disease-causing mutations involved in Tangier or Stargardt disease." (PMID 35361255, 2022). "In addition, the ABCA4 variant was not identified in the sister originally diagnosed with Stargardt disease." (PMID 33836713, 2021). "Although mutations in ABCA4 had been proposed as risk factors for age-related macular degeneration (AMD) a decade ago, more recent extensive phenotype–genotype studies have defined late onset Stargardt disease as a distinct entity that appears clinically similar to AMD." (PMID 34439845, 2021). "Screening of increasingly large numbers of patients from distinct populations would help to determine whether this broad spectrum of mutations can be explained by ethnic differences or is an indicator of extensive allelic heterogeneity of ABCA4 in Stargardt disease and other retinal diseases." (PMID 19028736, 2009). "We suggest that this distinct AMD phenotype exhibiting "diffuse-fine granular with peripheral punctate spots" reflects genetic alterations in ABCA4 and we speculate this distinct phenotype represents late onset Stargardt's macular dystrophy mimicking atrophic AMD." (PMID 17327825, 2007). "It gets downregulated in Stargardt’s disease and is an inhibitor of the membrane attack complex (MAC) assembled with the help of complement C3 and C5, and ABCA4." (PMID 40725253, 2025). "However, because some ABCA4 variants are not always disease-causing, the actual observed prevalence of Stargardt disease may be lower than the estimate from this study." (PMID 40960229, 2025). "LVs, with a packaging capacity of 8–10 kb, can accommodate therapeutic genes that surpass the limits of AAV, including ABCA4 (about 6.8 kb) and USH2A (about 15.6 kb), fitting for uses in Stargardt disease and Usher syndrome." (PMID 40725503, 2025). "ABCA4 pathogenic variants cause several retinal autosomal recessive disorders, including Stargardt disease (STGD1, OMIM #248200), cone-rod dystrophy (CORD3, OMIM #604116), and retinitis pigmentosa (RP19, OMIM #601718)." (PMID 37108442, 2023). "Forty Clinically important genes that are larger in size like ABCA4 and MYO7A for Stargardt disease and USH1B, respectively, can be packaged into EIAV." (PMID 35911417, 2022). "Patients of the ABCA4 and ELOVL4 cohorts also exhibited other classical symptoms reported in Stargardt disease: dyschromatopsia, central scotoma, photophobia, and delayed dark adaptation." (PMID 34073554, 2021). "Whether individuals with putative Stargardt Disease with one or zero detected ABCA4 mutations have non-traditional variation (e.g. promoter variants or epigenetic changes) missed by current mutation screening techniques or mutations in other genes is unclear at this time." (PMID 22863181, 2012). "In mice lacking ABCA4, a rescue of Stargardt’s disease phenotype was observed in mice treated with AAV5 expressing human RORA (hRORA)." (PMID 40725253, 2025).
Stargardt disease (continued). "Indeed, the insertion of 9 extra nucleotides due to the similar variant c.3191-11T>A in the ABCA4 gene causing Stargardt disease, could not be corrected by the single AON that could be designed, taking into account the limitations imposed by the target sequence region." (PMID 38520741, 2024). "The most important differential diagnoses of atrophic late AMD are the gene ABCA4, PRPH2, and BEST1 inherited macular dystrophies, including Stargardt disease (STGD1), Best disease (BD), or pseudo-Stargardt multifocal pattern dystrophy (PSPD) in late atrophic stages." (PMID 38132220, 2023). "Case 2a demonstrates ABCA4-RD with a phenotype of Stargardt disease without flecks, or bull’s eye maculopathy, which can be easily mistaken for cone dystrophy, such as the phenotype of Case 2b, which was a GUCY2D-associated AD cone dystrophy." (PMID 38066771, 2023). "To date, no therapy for ABCA4-related Stargardt disease exists, although both split-intein and DNA trans-splicing have been evaluated for their therapeutic potency in mouse models and pigs." (PMID 37852949, 2023). "Although the clinical presentation was consistent with Stargardt disease, both CLIA and extensive research genetic testing revealed no variants in ABCA4 or other known phenocopies, and EOG results revealed an abnormal light rise consistent with BVMD." (PMID 36264634, 2022). "Unlike human Stargardt disease, the Abca4 knockout mouse model does not degenerate structurally." (PMID 41326361, 2025). "There are several important instances where laboratory rodent engineered models fail to recapitulate the human disease; important examples including ABCA4-Stargardt disease, RDH5-retinopathy, or where the gene involved is not present in the mouse or rat genome e.g., EYS." (PMID 32260251, 2020). "The phenotypic intersection between Stargardt disease and PD is also apparent from a histopathological study of a PRPH2 p.Cys213Tyr PD donor eye, finding that RPE cells were distended with lipofuscin much in an analogous manner to donor eyes with defective ABCA4." (PMID 30630813, 2019). "Although Stargardt disease is not the most common condition in the Irish IRD patient cohort, it is very genetically homogeneous: 73% of sequenced Irish Stargardt pedigrees showed causative mutations in ABCA4, with many of the remainder having one identifiable ABCA4 mutation but not two." (PMID 27624628, 2016). "For a patient with a clinical diagnosis of Stargardt disease, WES analysis of the vision‐disorders panel genes and special focus on the Stargardt genes (ABCA4 and ELOVL4) did not result in a molecular diagnosis." (PMID 35191116, 2022).
retinal degeneration (76 papers, 2011 to 2026). Degeneration of the retina. "In various cohorts, ABCA4 mutations have been found to account for 2%–5% of non‐syndromic RP cases, confirming its role in peripheral retinal degenerations." (PMID 41458191, 2026). "Retinitis Pigmentosa (RP) is a less common but recognized ABCA4‐associated phenotype, typically involving severe, pan‐retinal degeneration." (PMID 41458191, 2026). "Several studies have reported different intronic variants in the ABCA4 gene associated with retinal degeneration." (PMID 40606666, 2025). "The clinical presentation of ABCA4 variants is heterogeneous, with retinal degeneration varying in severity and primarily affecting the macula or peripheral retina." (PMID 41465088, 2025). "Together, our results indicate that JC3 and JC4 protect the retina of Abca4-/-Rdh8-/- mice from retinal degeneration caused by bright light injury." (PMID 39808594, 2025). "For instance, imaging data were used to manually locate the fovea for participants with ABCA4-associated retinal degeneration who had parafoveal fixation." (PMID 40149532, 2025). "Retinal phenotypes associated with genetic defects in ABCA4 are collectively known as ABCA4-associated retinal degenerations (ABCA4R), a group of recessively inherited disorders associated with a high allelic heterogeneity." (PMID 39162841, 2024). "The purpose of this study was to analyze and molecularly describe the largest group of patients with ABCA4-associated retinal degeneration in Latin America." (PMID 39162841, 2024). "Overall, in silico analyses of ABCA4 can provide a valuable tool for understanding the molecular mechanisms of retinal degeneration and their pathogenic impact." (PMID 37108442, 2023). "Functional declines of the retinas were observed in Abca4−/−/Rdh8−/− animals, along with retinal degeneration, which was linked to an aberrant buildup of bis-retinoids." (PMID 36227868, 2022). "Over 1,500 variants in the ABCA4 locus cause phenotypes ranging from severe, early-onset retinal degeneration to very late-onset maculopathies." (PMID 35353811, 2022). "It has been shown that the loss of clearance mechanism caused by mutations in ABCA4, a gene of the ATP-binding cassette transmembrane protein, which eliminates all-trans-retinal from rod photoreceptors, causes retina degeneration in STGD." (PMID 36227868, 2022). "It is important to know more about the genotype–phenotype correlation and the progressive pattern for patients with ABCA4-associated retinal degeneration." (PMID 33261146, 2020). "This is the first cohort study of ABCA4-associated retinal degeneration in Taiwan with wide spectrums of both genotypic and phenotypic characteristics." (PMID 33261146, 2020). "The severity of disease-causing variants in ABCA4 is reported to be associated with the onset age of ABCA4-associated retinal degeneration." (PMID 33261146, 2020). "This curve should be of importance to scientists attempting to develop therapeutic interventions for ABCA4-associated retinal degeneration, such as gene therapy or pharmacological agents." (PMID 33261146, 2020). "Several studies have attempted to establish the natural history of ABCA4-associated retinal degeneration and disease progression." (PMID 33261146, 2020). "Patients with ABCA4-associated retinal degeneration commonly present with progressive bilateral central vision loss." (PMID 33261146, 2020). "Few studies regarding ABCA4-associated retinal degeneration have been conducted in the Taiwanese population." (PMID 33261146, 2020). "Disruption of REP-1, PROM1, ELOVL4, or ABCA4, each involved in lipid processing, causes early-onset retinal degeneration." (PMID 29321376, 2018). "Group (b) was very small with only 9 genes, and it did not make a cluster of functionally related GO terms, although 6 of 9 genes were annotated as causal genes for retinal degeneration (Abca4, Elovl2, Fscn2, Nxnl1, Pde6c, and Pde6h)." (PMID 24747725, 2014).